PIGF (phosphatidylinositol glycan anchor biosynthesis class F)
Diseases named in the same sentence as PIGF in open-access papers (continued):
Sharing a sentence is not in itself a finding about the gene and the disease.
proliferative diabetic retinopathy (1 paper, 2023). Advanced retinopathy due to diabetes mellitus characterized by the formation of new vessels in the retina. "We detected up-regulated levels of VEGF-A (p = 0.001), PIGF (p<0.001), Angiopoietin-1 (p = 0.005), Angiopoietin-2 (p<0.001), IL-1β (p = 0.012), and IL-8 (p = 0.018) in proliferative diabetic retinopathy samples." (PMID 36662891, 2023).
prostate carcinoma (1 paper, 2024). A carcinoma that arises from epithelial cells of the prostate gland. "The bioinformatics study performed by the GO functional analysis tool provided by the TNM plotter confirmed the increased expression of PIGF in prostate cancers compared to metastasis (p = 5.14 × 10−2) Similar data have been observed for HIF-1α expression." (PMID 39457506, 2024).
pulmonary hypertension (1 paper, 2019). Increased pressure within the pulmonary circulation due to lung or heart disorder. "Moreover, except RHOQ and PIGF, the other five genes showed significant associations with uric acid (UA) level (top adjusted p = 1.89 × 10−5 – 0.024 for each gene)—a useful biomarker of vascular dysfunction (e.g. pulmonary hypertension)." (PMID 34691999, 2019).
rectal cancer (1 paper, 2025). A primary or metastatic malignant neoplasm that affects the rectum. "PIGF, VEGF, and VEGF-C are known promotors of endothelial cell proliferation and previous research in rectal cancer biopsies has shown diminished endothelial cell proliferation after radiotherapy." (PMID 39965288, 2025).
retinal diseases (1 paper, 2016). "Conbercept is a VEGF and PIGF dual antagonist and has become an increasingly common intervention for the treatment of retinal diseases in China." (PMID 27922068, 2016).
Sepsis (1 paper, 2023). Sepsis is defined as life-threatening organ dysfunction caused by a dysregulated host response to infection. "While IL-6, PIGF, and CRP were also significantly elevated in post-Sepsis patients compared to controls, the observed differences in TNFα, Tie-2, Flt-1, IL-7 and bFGF were unique to the post-COVID group." (PMID 36844209, 2023).
tumor (57 papers, 2010 to 2025). "VEGF, FGF, and PIGF have been related to excessive cell proliferation, angiogenesis, and the modulation of inflammatory response implicated in tumor development and progression." (PMID 34198488, 2021). "In animal studies PIGF overexpression correlates with a decrease in tumor growth by stabilization of the tumor vasculature caused by heterodimerization with VEGF, that neutralizes its potency." (PMID 27608016, 2016). "The release of tumor-released chemokines such as CSF-1 and PIGF attract tumor-associated macrophages (TAM) to the microenvironment, which in turn release multiple factors stimulating invadopodia." (PMID 22481931, 2012). "PIGF potentially plays roles in wound healing, tumor growth, and collateral vessel formation when ischemia occurs." (PMID 40004604, 2025). "VEGFR-1 is one of the VEGF receptors, which in tumor cells can be activated by its ligands (such as VEGF-B and PIGF) to significantly increase the invasion capabilities of the tumor cells." (PMID 38667800, 2024). "Overall, T cell activation status of circulating and tumour-infiltrating T cells correlated with response to treatment and adverse tumour biology as well as levels of immunosuppressive and pro-angiogenic PIGF and VEGFA present within the TME." (PMID 35986757, 2023). "For example, tumor growth and mesenteric metastases from orthotopic transplants were increased by HFD-induced placental growth factor (PIGF)/VEGFR-1 signaling that repolarized macrophages towards a pro-tumorigenic phenotype (M2) in the tumor microenvironment." (PMID 37648285, 2023). "Polymeric NPs were developed to deliver vascular endothelial growth factor (VEGF) siRNA and placental growth factor signaling (PIGF) siRNA to both tumor cells and TAMs, leading to suppressed tumor growth and metastasis." (PMID 36810108, 2023). "Other stimuli, such as oncogenes and hormones, are also suggested to upregulate PIGF, making their presence in tumor cells and the tumor microenvironment all the more likely." (PMID 37626639, 2023). "The proteins secreted by the primary tumor, VEGF, and placental growth factor (PIGF) affect the bone marrow mesenchymal stem cells, causing the BMDCs to go to the preferred site for metastasis before the disseminated tumor cells do." (PMID 37174117, 2023). "In tumor cells, the expression of PIGF protein have been shown to undergo an angiogenic switch that promotes tumor vascularization." (PMID 36034829, 2022). "This upregulation of PIGF sustains the survival and metastasis of tumor cells while stimulating cardiac angiogenesis." (PMID 36034829, 2022). "For instance, Δ9-THC reduced both angiopoietin-2 (Ang-2) and placental growth factor (PIGF) production in tumor cells, whose effect in neoplasms and chronic myeloproliferative diseases is well known." (PMID 34202812, 2021). "Accordingly, the in vivo blockage of PIGF or FGF pathway normalizes the tumor vessels and improves the efficacy of VEGF-targeted therapy." (PMID 33916438, 2021). "PIGF is also expressed in some other paediatric CNS tumours, such as gliomas, ependymomas, and AT/RT tumours, making this approach a therapeutic opportunity." (PMID 34831165, 2021). "The role of PIGF in tumour promotion is controversial, with some studies showing the involvement of PIGF in tumour growth and others showing the opposite." (PMID 34831165, 2021). "Through the release of VEGFB and PIGF, tumor cells can enhance haematopoiesis and monocyte recruitment." (PMID 31447834, 2019). "Preoperative serum levels of angiogenesis factors, for example, such as placenta growth factor (PIGF), combined with circulating tumor cell levels, have been identified as independent predictors of poor recurrence-free survival in a series of 107 patients." (PMID 27935861, 2017). "PIGF contributes to angiogenesis in pregnancy, wound healing, ischemic conditions, and tumor growth." (PMID 24991539, 2014).
tumor (continued). "In addition, the administration of PEGV-200 dramatically downregulated the expressions of pAKT, pERK, and pIGF-IR in HepG2 and HepG2-SR tumor tissues, which became primarily localized in residual small clusters of tumor cells." (PMID 36276070, 2022). "“Angiogenic switch” activators are the tumor microenvironment; mutation in oncogenes or tumor-suppressor genes; pro-angiogenic molecules (VEGF, FGF-2, EGF, PDGF, PIGF, and MMPs); and anti-angiogenic factors (thrombospondin, angiostatin, tumstatin, and endostatin)." (PMID 35454076, 2022). "In various cancers, PIGF is involved in tumor immune escape and metastasis." (PMID 35545767, 2022). "In mouse models targeting PIGF lead to a reduction of tumor growth." (PMID 34041019, 2021). "These disappointing results might be explained by a decrease in PIGF expression during tumor progression, in particular after treatment with TMZ." (PMID 33918704, 2021). "It has been reported that PIGF takes part in cancer as a paracrine and autocrine factor, promoting proliferation and as a stimulator of angiogenesis of tumor cells, and this might explain the high concentration of PIGF in our study." (PMID 28486560, 2017). "Indeed, the release of other proangiogenic factors beyond VEGF like placenta growth factor (PIGF), fibroblast growth factor and others can be stimulated to supply the hypoxic growing tumor." (PMID 24902850, 2014). "PIGF inhibitors are able to reduce the angiogenesis and tumor cell motility." (PMID 24991539, 2014). "VEGF-A and PIGF, which are major pro-angiogenic factors associated with cancer angiogenesis and are pro-tumorigenic and Flt-1, also known as vascular endothelial growth factor receptor 1 (VEGFR-1), is a high-affinity tyrosine kinase receptor for VEGF involved in tumor growth and metastasis." (PMID 35154142, 2022). "In vivo studies have shown that by blocking PIGF production in CAFs, the stiffness of the tumor could be weakened, thereby improving the hypoxic status, and enhancing the blood supply of the tumor, which was more conducive to the application of chemotherapeutic drugs." (PMID 35971182, 2022). "Importantly, we also found activation of angiogenesis-regulating pathways including PIGF, VEGF, and RAF in painful tumors, suggesting that already existing drugs, such as the anti-angiogenic drug Avastin or compounds targeting PIGF, can be utilized for management of pain or tumor size in SWNTS." (PMID 33025139, 2021). "Other studies have been reporting the tumor vessels normalization in hepatocellular carcinoma models and the improved efficacy of VEGF-targeted therapy in ocular disease as outcomes of PIGF blockage." (PMID 33916438, 2021). "Western blot analysis further indicated that inhibition of miR-183-5p led to a down-regulation in the expression of VEGFA, VEGFAR2, ANG2, PIGF, MMP-2 and MMP-9 along with up-regulated FOXO1 expression in tumor tissues (p < 0.05)." (PMID 32364530, 2020). "VEGF protein family consists of VEGF A, B, C, D, F, placental growth factor (PIGF), and their receptors VEGFR-1, 2, 3, among which VEGF-A (or VEGF) and VEGFR-2 are widely accepted as mostly responsible for tumor development." (PMID 30702616, 2019). "Patients with higher secretion of PIGF, TIE-2, ICAM-1 or VCAM-1 from their tumour explants displayed higher nodal status, reflective of a more aggressive cancer phenotype." (PMID 31217905, 2019). "PIGF, a VEGF homolog, is expressed in low levels in normal tissue and can be overexpressed in tumor cells." (PMID 24991539, 2014). "In particular, in MDA-MB-231 and MRC5 cells, SR and CBD affect the secretion of growth factors involved in proliferation and angiogenesis (bFGF, FGF4, -6, -7, VEGF-D, PIGF, PDGF-AB, and -BB), tumor metabolism (IGFII, IGBPs), and immune response (GCSF, MCSF, TGF family members)." (PMID 37686233, 2023). "Similarly, PIGF, a VEGF homolog known to increase angiogenesis by binding to VEGFR-1 is expressed by tumour, proangiogenic, inflammatory, stromal, and endothelial cells." (PMID 34099013, 2021).
tumor (continued). "During tumor progression, angiogenesis (formation of new vessels from preexisting vascular network) has been pathologically accelerated by multiple proangiogenic factors such as vascular growth factor (VEGF) and placenta growth factor (PIGF)." (PMID 30596096, 2018). "When seeking the VEGFR1 ligands responsible for this cascade, we found that VEGF-A, but not placental growth factor (PIGF), was expressed both in vivo and in vitro, at least in our tumor models." (PMID 29212030, 2017). "Additionally, signal molecules produced by tumor cells, such as lactate, HRG/PIGF, chemokine ligand 2 (CCL2), soluble colony-stimulating factor 1 (sCSF1), and POSTN, play critical roles in macrophage polarization." (PMID 27683110, 2016). "In contrast, HT-1080s secreted placental growth factor (PIGF), a potent tumor angiogenic factor not detected with fibroblasts." (PMID 23226527, 2012). "The possible mechanism is that angiogenesis in the tumor may be driven by additional factors, such as fibroblast growth factor 1 (FGF-1), FGF-2, transforming growth factor-β (TGF-β), platelet-derived endothelial cell growth factor (PD-ECGF), and placental growth factor (PIGF)." (PMID 23799045, 2013). "Excluding genes not detected (OPN4, PIGF), gene NONO was more highly expressed in BRCA tumor tissue (BRCA tissue) than in normal breast tissue (Normal breast tissue)." (PMID 40826746, 2025). "An IHC analysis was implemented on gene expressions in BRCA tumor tissue and normal breast tissue, with HR values >1 (NONO, OPN4, PIGF) in the Cox model by using the Human Protein Atlas database." (PMID 40826746, 2025).
cancer (14 papers, 2015 to 2024). A tumor composed of atypical neoplastic, often pleomorphic cells that invade other tissues. "Furthermore, upregulation of IGF-I/IGF-IR signaling is associated with the mechanisms of chemoresistance as the pIGF-IR expression is increased in various drug-resistant cancers." (PMID 35267503, 2022). "PIGF signaling activates inflammatory cytokine releasing, such as IL-1β and IL-6, to promote angiogenesis in several types of cancer." (PMID 35895109, 2023). "By releasing these cytokines, PIGF modulates the innate immune system by activating macrophages and attracting monocytes leading to an increased inflammatory state in wound healing and cancer." (PMID 37626639, 2023). "PIGF is upregulated in many advanced stages of cancer and may also play a role in monocyte recruitment, separate from its stimulation of VEGF secretion." (PMID 37626639, 2023). "ANG2 and PIGF expression positively correlated with cancer cell stemness." (PMID 35545767, 2022). "We suggest that the PIGF secreted by carcinoma cells could also be part of the activation signaling of fibroblasts." (PMID 34198488, 2021). "The analysis of the conditioned medium showed a different pattern of the secreted growth factors VEGF, FGF, and PIGF, which were secreted at significantly higher levels in the CM of EMC cultures compared with the CM of same carcinoma cells cultured on plastic." (PMID 34198488, 2021). "It was previously reported that cancer cells recruit BMDCs through secretion of soluble factors, including SDF-1, VEGF, MMP-9, placental growth factor (PIGF), IL-1 beta, and granulocyte macrophage colony stimulating factor (GM-CSF)." (PMID 26416452, 2015). "PIGF (placental growth factor), is a member of the VEGF family, which can bind VEGFR1 with high affinity, plays a key role in pathological angiogenesis, especially in cancer, cardiovascular, autoimmune and inflammatory diseases." (PMID 36119065, 2022). "The therapeutic target genes, such as CDK6, HDAC2 and PIGF, exhibited enhanced expression levels in the EMT meta program, confirming that drugs targeting these genes may have significant therapeutic responses in such cancer cell subpopulations." (PMID 38944814, 2024). "Apart from molecular targets expressed in cancer cells of the three types of programs, CD52, CDK6, HDAC2, and PIGF were specifically expressed in inflammatory or EMT meta programs, indicating that drugs against these targets may respond in specific cancer cell subpopulations." (PMID 38944814, 2024).
genetic disease (1 paper, 2024). "Interestingly, human mutations affecting PIGL and PIGF, and up to 15 other GPI biosynthesis pathway genes have been related to human genetic disease with common clinical features such as congenital heart defects and neurodevelopmental disorders." (PMID 38819479, 2024).
kidney disease (1 paper, 2016). "Our case report suggests that starting intensive dialysis early in pregnancy is safe and concentration of angiogenic factors are similar to those reported for patients without kidney disease, except for PIGF levels, which are somewhat higher." (PMID 26909159, 2016).
PIGF also shares sentences with these, for which no sentence is quoted: glioma (3 papers); Stroke (2); Alzheimer disease (1); atopic dermatitis (1); bone disorder (1); cardiac diseases (1); cholangiocarcinoma (1); choroidal neovascularization (1); depression (1); endometriosis (1); hepatoblastoma (1); hypothyroidism (1); ischemia (1); kidney damage (1); lipoblastoma (1); liver cancer (1); lymph node metastasis (1); medulloblastoma (1); Multiple Organ Failure (1); neurodevelopmental disorder (1); non-small cell lung carcinoma (1); ovarian carcinoma (1); pancreatic cancer (1); pancreatic ductal adenocarcinoma (1); pleomorphic adenomas of the salivary gland (1); Pleural effusion (1); pregnancy disorder (1); retinopathy (1); Stillbirth (1); type 2 diabetes mellitus (1).